CD4 (CD4 molecule)
Diseases named in the same sentence as CD4 in open-access papers (continued):
Sharing a sentence is not in itself a finding about the gene and the disease.
HIV-1 infection (continued). "The results reported here show that PC liposomes can down-modulate the expression of CD4 in human type-1 macrophages but not in helper T cells, without affecting cell viability, and hence can interfere with the initial steps of HIV-1 infection." (PMID 35663973, 2022). "HIV-1 DNA levels in PBMC of acute, chronic, and suppressed HIV-1 infection tend to be lower, generally ~102 to 103 copies per 106 PBMC, or at most 1% of memory CD4 T cells in acute and chronic untreated infection, and 1 to 10−1 copies per 106 PBMC in cART-treated patients." (PMID 35510859, 2022). "ECs spontaneously control HIV-1 infection, as evidenced by undetectable levels of viremia, stable CD4-positive (CD4+) T cell counts, and no signs of clinical progression." (PMID 35708287, 2022). "Unlike sCD4 or D1D2, 2DLT did not enhance HIV-1 infection in CD4-/CCR5+ cells, making it safer to use." (PMID 35038908, 2022). "HIV-1 infection remains non-curative due to the latent reservoir, primarily a small pool of resting memory CD4+ T cells bearing replication-competent provirus." (PMID 35774399, 2022). "Immune-related genes, including CD4, CCL5, IFN-γ, STAT1, APOBEC3G, CD45, and ICAM-1, in PBMCs act a key role in immune responses against HIV-1 infection, and could, hence, be correlated with CD4 T cell depletion in HIV-1 pathogenesis." (PMID 36380676, 2022). "To more closely approximate natural HIV-1 infection, we next investigated the role for ISG15 with and without an IFN-I prime in primary human CD4+ T cells, the physiological target of HIV-1 infection." (PMID 35333911, 2022). "The finding claiming that high frequencies of Treg persisted during the initial phase of HIV-1 infection may be due to the methods used to identify Tregs which are based on Foxp3 and CD25 expression both induced as well following CD4 T-cell activation." (PMID 35633761, 2022). "In this study, we show that the combination of a powerful erythroid-specific expression system and transgene codon optimization yields high expression levels of the HIV-1 receptors CD4 and CCR5 on enucleated RBCs to generate viral traps that potently inhibit HIV-1 infection in vitro." (PMID 33723514, 2021). "Applying the CD4 aptamer–siRNA to humanized mice resulted in efficient protection against HIV-1 infection with no detectable viral load up to 12weeks in chimera treated mice group." (PMID 34858370, 2021). "Similarly, tryptophan metabolism promotes HIV-1 infection and transcription by the activation of a ligand-activated transcription factor aryl hydrocarbon receptor (AHR) in CD4+ T cells." (PMID 34616406, 2021). "Studies have shown that platelet-lymphocyte complex formation increases during HIV-1 infection and that the P-selectin glycoprotein ligand-1 (PSGL-1) on CD4+ T cells and P-selectin (CD62P) on platelets expressed after platelet activation mediate the interactions between platelets and lymphocytes." (PMID 34987521, 2021). "Robust CD4+ and CD8+ T cell responses were also detected after DENV and HIV-1 infection." (PMID 33692812, 2021). "CCL-19 neither elicits T cell activation nor induces CCR5 or CXCR4 expression, but enhances cis HIV-1 infection of resting CD4+ T cells." (PMID 33688006, 2021). "The NTP-mediated latency reversal of HIV-1 infection is another novel observation of this study and suggests a role for dominant RONS (or a combination of RONS) delivered by or induced by NTP in the reversal of the quiescent state of CD4+ T cells." (PMID 33647028, 2021). "After administration of a potent reverse transcriptase inhibitor, viral production was blocked in circulating CD4+ T cells but not in tissue macrophages, demonstrating that tissue macrophages can sustain HIV-1 infection alone." (PMID 33897659, 2021). "As expected, GSK261805A inhibited HIV-1 infection in CD4+ T cells but not in ACH2 cells, confirming RORC2 as the target mediating the phenotype." (PMID 34819367, 2021).
HIV-1 infection (continued). "In vivo longitudinal patterns of HIV-1 integration sites were studied in sorted resting and activated CD4+ T cells from 10 HIV-1–infected individuals, who were diagnosed during acute (<3 months postinfection) or recent (3–6 months postinfection) HIV-1 infection." (PMID 33784259, 2021). "After 50 days of HIV-1 infection, more than 50% of CD4+ T cells in 8 out of 10 mice carried a disrupted CCR5; these mice also had lower plasma viremia and higher CD4+ T cell counts in their peripheral blood than those of mice engrafted with wild-type CD4+ T cells." (PMID 34122453, 2021). "In summary, we systematically compared plasma virome in MSM with or without HIV-1 infection and compared the virome changes at different CD4+ T cell counts." (PMID 33952659, 2021). "Jurkat T cells were early on used to decipher the fundamental molecular biology of TCR/CD3 signaling and are now a commonly used CD4+ T cell line to study HIV-1 latency, making them an ideal system to investigate TCR/CD3 reactivation response in the context of HIV-1 infection." (PMID 33465149, 2021). "The negative correlation observed between STING and CD4+ T cell level can be explained by understanding the immunological characteristics of acute HIV-1 infection without treatment." (PMID 33858455, 2021). "Vpu is an HIV-1 accessory protein generated from Env/Vpu encoded bicistronic mRNA and localized in cytosolic and membrane regions of cells capable of being infected by HIV-1 and that regulate HIV-1 infection and transmission by downregulating BST-2, CD4 proteins levels, and immune evasion." (PMID 34452331, 2021). "Recently, in vitro study reported that exosomes shed from CD4+ T cells not from CD4- T cells well inhibit HIV-1 infection, proposing that exosomal CD4 interacts with HIV-1 envelope proteins, neutralizing HIV-1 and preventing its interaction with target cells." (PMID 34575480, 2021). "Also, the interaction between the activation of the glycoprotein and the CD4+ T cells activates the PI3K pathway responsible for regulating the migration of T cells and promoting the entry of viral particles after HIV-1 infection." (PMID 35058917, 2021). "More importantly, GPI-m36.4-modified human CD4+ cells (CEMss-CCR5) were exceptionally resistant to both CCR5- and CXCR4-tropic HIV-1 isolates and had a robust selective survival advantage over unmodified cells following HIV-1 infection." (PMID 33462383, 2021). "Furthermore, Ibalizumab, a CD4-directed, post-attachment inhibitor, was approved by the U.S. FDA to treat HIV-1 infection and multidrug-resistant HIV-1 infection in combination with other antiretroviral(s)." (PMID 33807292, 2021). "Eligible cohort participants were not taking antiviral medications, and those with HIV-1 infection had a CD4 count >200 cells/mm3." (PMID 34153032, 2021). "Importantly, we found a significant reduction in CD73+ CD4+ T cells in early primary HIV-1 infection, with these cells further reduced during chronic HIV-1 infection, confirming and extending previous results." (PMID 33477692, 2021). "Synergistic upregulation of PD-1 and TIGIT is linked to increased inhibitory function, poor functionality of HIV-1 specific T-cell responses and is inversely correlated with CD4% and CD4/CD8 ration in HIV-1 infection, suggesting that this population resembles highly exhausted CD8 T-cells." (PMID 34712231, 2021). "It was observed that HIV-1 infection downregulates the expression of NEAT1 lncRNA leading to the reduction of the number of host-protective paraspeckle bodies, hence increased HIV-1 expression within CD4+ T lymphocytes." (PMID 34737736, 2021). "Given that CD4 acts as a receptor for IL16 in T cells the function of IL16 on infectious diseases has mainly been investigated in HIV-1 infection." (PMID 34630361, 2021). "As expected, CD4 + T cell populations are more easily restored after effective cART, even if not initiated as soon as HIV-1 infection diagnosis is confirmed." (PMID 34873266, 2021).
HIV-1 infection (continued). "We have demonstrated that HIV-1 infection promotes the formation of platelet-CD4+ T cell aggregates, and the upregulation of CD62P could partly explain the elevated frequencies of platelet-CD4+ T cell aggregates in patients infected with HIV-1." (PMID 34987521, 2021). "Ingenol and gingerol assist CD4+ T cells in maintaining high cell viability to fight HIV-1 infection without disrupting viral replication." (PMID 34903920, 2021). "Overall, both non-productive and productive CD4+ T cell infection was robust in both CSF and PB during acute HIV-1 infection." (PMID 34874976, 2021). "One of those markers, CCR5, appears to make these cells particularly vulnerable to HIV infection and our results detail not only their depletion, beginning very early in the course of primary HIV-1 infection, but also proviral infection of the remaining CD73+ CD4+ T cells." (PMID 33477692, 2021). "In addition to that in macrophages, Vpr enhances HIV-1 infection and HIV-1 gene expression in CD4+ T cells." (PMID 34835114, 2021). "The reduced proportions of CD73+ CD4+ T cells in chronic HIV-1 infection meant that we needed to use cryopreserved PBMC obtained by leukopheresis from a cohort of untreated patients, to sort CD73+ and CD73-negative subsets of memory CD4+ T cells." (PMID 33477692, 2021). "Even though the prevalence of anellovirus was also the same here in MSM and after HIV-1 infection, its abundance greatly increased after HIV-1 infection and was negatively correlated with CD4+ T cell counts, which could be restored by ART." (PMID 33952659, 2021). "DDX3 inhibition also resulted in the downregulation of BIRC5, critical to cell survival during HIV-1 infection, and selectively induced apoptosis in viral RNA-expressing CD4+ T cells but not bystander cells." (PMID 33931637, 2021). "In acute untreated HIV-1 infection, the circulating CD161+ CD4+ T cell population decreased in frequency, as did absolute cell counts starting from peak viral load, with elevated levels of activation and exhaustion markers expressed throughout acute HIV-1 infection." (PMID 33322496, 2020). "In addition to CD4, both CCR5 and CXCR4, HIV-1 co-receptors, are detected on human KCs isolated from non-HIV-1 individuals, suggesting that KCs are permissive for HIV-1 infection." (PMID 32612603, 2020). "In this study, we investigate CD161+ CD4+ T cell frequency, phenotype, and function in a longitudinal manner in individuals prior to infection, and in acute HIV-1 infection (AHI) with or without ART." (PMID 33322496, 2020). "HIV-1 infection can persist for decades despite effective antiretroviral therapy (ART), due to the persistence of infectious latent viruses in long-lived resting memory CD4+ T cells, macrophages, monocytes, microglial cells, and other cell types." (PMID 33383617, 2020). "While IFNLs have been shown to skew T lymphocyte responses, their impact in treated HIV, in particular the potential for IFNL4 expression to modulate the CD4+:CD8+ T-cell ratio in the context of treated HIV-1 infection has not been explored to date." (PMID 32295609, 2020). "Only upon TCR or PHA activation of CD4+ T cells, did the level of IFNLR1 mRNA expression match or surpass that seen in CD8+ T cells, in turn leading to greater ISG induction and ultimately inhibition of HIV-1 infection by IFN-λ3 treatment." (PMID 32353085, 2020). "Treatment with IDB did not change the expression of antiapoptotic Bcl-2, but increased the expression of antiapoptotic Bcl-xL and Mcl-1 in CD4+ T cells with or without HIV-1 infections." (PMID 32792548, 2020). "Early initiation of anti-retroviral treatment (ART) during acute HIV-1 infection restored the functionality of peripheral blood CD161+ CD4+ T cells, but not their frequency." (PMID 33322496, 2020).
HIV-1 infection (continued). "This restriction occurs at the step of reverse transcription, is independent of interferon stimulation, and limits HIV-1 infection in key target cells of HIV infection including CD4+ T cells and monocyte-derived dendritic cells." (PMID 32282853, 2020). "Similarly, Candida albicans-specific CD4+ T cells are also preferentially infected by HIV-1 and depleted during progressive HIV-1 infection." (PMID 31910871, 2020). "Based on previous studies and our data, we propose a model where a “dead-end” pathway for HIV-1 infection can contribute to viral dissemination: HIV-1-infected APCs or T cells migrate to the lymph node and transmit the virus to uninfected CD4+ T cells during cell-to-cell contact." (PMID 31919342, 2020). "Taken together, these results suggest that high CD4+DPP4+ T cell frequencies correlate with more favorable prognostic surrogate markers of HIV-1 infection in women but not in men." (PMID 32946499, 2020). "CD4+ T cells expressing Glut1 show higher levels of activation marker as well as HIV-1 co-receptor CCR5 compared with CD4+Glut1- cells and blockade of glycolysis pathway by PI3K inhibitor could suppress HIV-1 infection in vitro." (PMID 33117366, 2020). "IL-7 and IL-2 were previously used to increase CD4+ T cell counts in HIV-1 infection, however, no improvement in their function were reported." (PMID 33384690, 2020). "Because CD4+ memory T cells are the major reservoir for latent HIV-1, we hypothesize that targeting autophagy would facilitate the elimination of latent HIV-1 infection." (PMID 32792548, 2020). "Although it may seem counter intuitive that HIV-1 infection stimulates expression of MIP-1β, the function of this chemokine is to recruit CD4+ T-lymphocytes to the site of infection, thereby enhancing the number of target cells for HIV-1 replication." (PMID 31487324, 2019). "As expected, NP CD4+ T cells were able to support cis HIV-1 infection before ART but not after ART initiation." (PMID 31304185, 2019). "In this in vitro study, calcitriol induced a protective effect reducing HIV-1 infection of CD4+ T from non-exposed healthy individuals, irrespectively of the X4- or R5-viral tropism." (PMID 31550271, 2019). "As IL-7Rα signaling in CD4+ T cells may affect TFH cell function and is adversely affected by HIV-1 infection, we have examined the relationship of IL-7Rα expression on ICOS+ cTFH cells with PcP-specific IgG2 antibody responses." (PMID 31068934, 2019). "In contrast, we found that overriding the enzymatic activity of arginase-2 by l-arginine supplementation did not abrogate the enhanced HIV-1 infection in CD4+ T cells when cocultured with CECs." (PMID 31772057, 2019). "This also directly correlated with the production of ISGs, as exemplified by tetherin/BST2, which was preferentially induced by HIV-1 infection in CD4 T cells and macrophages in peripheral circulation but was not induced in splenic CD4 T cells or macrophages." (PMID 30867315, 2019). "In untreated infection, HIV-1 infection occurs mostly in effector memory and not naïve CD4+ T cells, in part because memory, particularly activated memory (CD127lo), CD4+ T cells express higher co-receptor levels." (PMID 31507594, 2019). "Although bone marrow HIV-1 infection was not measured in the current study, the progressive decline of CD4+ T cells indicated that active viral replication was rapidly established in the hu-HSC mouse bone marrow." (PMID 30873181, 2019). "Although this process was most marked for already activated CD4+ T cells, CECs significantly enhanced HIV-1 infection in nonactivated CD4+ T cells as well." (PMID 31772057, 2019). "The responders to P6, P8, and P9 peptides showed both significantly lower pVL and higher CD4 count than nonresponders, suggesting a protective role against HIV-1 infection in vivo." (PMID 30674626, 2019).
HIV-1 infection (continued). "Interestingly, deep sequencing of HIV-1 infected human CD4+ T cells and SUP-T1 cells (a human T cell line) revealed hundreds of differentially expressed lncRNAs over the course of HIV-1 infection." (PMID 31336952, 2019). "For example, abortive HIV-1 infection in quiescent lymphoid CD4 T cells leads to CD4 T cell pyroptosis independent of the NLRP3 inflammasome." (PMID 30634407, 2019). "To confirm that the up-regulation of MALAT1 upon HIV-1 infection is universal, we also used PHA-P-activated primary CD4+ T cells, CD4+ T-lymphocyte cell line Hut/CCR5, Jurkat and H9 cells for infection with either pseudotyped HIV-Luc/NL4-3 or replication competent HIV-1/NL4-3." (PMID 30788509, 2019). "Unlike HIV-1 infection of activated CD4+ T-cells, which is characterized by high levels of virus replication, resting memory CD4+ T-cells support only restricted transcription of latent provirus." (PMID 31487807, 2019). "By using a Transwell system, we observed that increased HIV-1 infection in CD4+ T cells does not necessarily depend on cell-cell interactions." (PMID 31772057, 2019). "Stimulation of T cell lines or primary CD4+ T cells expressing chimeric antigen receptors supported HIV-1 infection regardless of affinity for ligand; however, only signaling by the highest affinity receptor facilitated HIV-1 expression." (PMID 31116788, 2019). "Consistent with activated CD4+ T cells, we found that CECs increased HIV-1 infection in nonactivated CD4+ T cells." (PMID 31772057, 2019). "However, the role of activated CD4+ T cells in HIV-1 vaccines is controversial because these cells can act as both immune effectors and infection targets for HIV-1 infection." (PMID 30524435, 2018). "Adaptive immunity against HIV-1 infection is mediated by specific CD4+ and CD8+ lymphocytes and by neutralizing and non-neutralizing antibodies." (PMID 29467764, 2018). "In addition, there have been studies that have revealed a CD4 and CCR5 or CXCR4 independent method for HIV-1 infection of macrophages." (PMID 30619107, 2018). "Early studies demonstrated that restriction to HIV-1 infection in non-cycling quiescent macrophages and resting CD4+ T cells occurred during reverse transcription." (PMID 29587790, 2018). "Both methods of CD4+ T-cell quantification in spleen tissues, including flow cytometry as well as IHCS and QIA, consistently demonstrated much less CD4+ T-cell depletion during SIVcpz infection compared with HIV-1 infection." (PMID 29615603, 2018). "In this study, we have found that the cell surface levels of this inhibitory receptor are increased on CD4+ T cells after HIV-1 infection and it is not reverted by cART." (PMID 30083165, 2018). "Because productive HIV-1 infection predominantly occurs in activated CD4 T cells, it is implicit that HIV-1 infected cells are less permissive to egress cues compared to uninfected CD4 T cells that normally travel through the germinal center." (PMID 29499057, 2018). "Taking into consideration that HIF-1α plays a central role in the control of glucose metabolism and in CD4+ T cell functionality, we aimed to study whether HIF-1α activity was modulated during HIV-1 infection." (PMID 30206166, 2018). "Moreover, ectopic expression of Langerin in CD4+/CCR5+ U87 cells, a human glioblastoma cell line, also strongly inhibits HIV-1 infection in a huTRIM5α-, ATG16L-dependent manner." (PMID 28946621, 2017). "Regardless of the route of transmission, acute HIV-1 infection is characterized by high levels of replication and CD4+ T cell depletion in the gastrointestinal (GI) tract." (PMID 28241075, 2017). "In HIV-1 infection, we also observed distinctive expression pattern of VRGs in progressors and non-progressors in independent datasets on whole blood or CD4+ and CD8+ T cells." (PMID 28771541, 2017). "Events following IVAG HIV-1 infection; viral dissemination and CD4 depletion, were not affected by these parameters." (PMID 29127409, 2017).